TNF (tumor necrosis factor)
Diseases named in the same sentence as TNF in open-access papers (continued):
Sharing a sentence is not in itself a finding about the gene and the disease.
breast carcinoma (continued). "The treatment of HER2-expressing breast cancer cells with Th1 cytokines, IFN-γ and TNF-α can cause oncogene inactivation of HER2 followed by a cell-cycle arrest of the tumor cells." (PMID 29725336, 2018). "It was observed that H3K27me3 enrichment was reduced in Tnf promotor in Kupffer cells following liver failure, which is supported by others, showing TNF gene is regulated under H3K27me3 in breast cancer cells." (PMID 29789597, 2018). "In this study, we analyzed the effect of TNF on ganglioside biosynthesis and expression in breast cancer cells from different molecular subtypes." (PMID 29698439, 2018). "Suppression of VASP is associated with TNF-α and HIF-1α induced inhibition of breast cancer cell adhesion and proliferation.Downregulation of VASP expression inhibits breast cancer cell migration and invasion." (PMID 30271395, 2018). "A. canaliculatum ethanolic extract (ACE) inhibits TNFα-induced migration of MDA-MB-231 metastatic breast cancer cells and prevents TNFα-induced CXCR3 and CXCL10 expression through inhibition of the IκB kinase (IKK)-mediated NF-κB pathway." (PMID 30177620, 2018). "Fortunately, we found that IKKβ mediates ARD1 degradation during the process of TNFα-induced cell growth of breast cancer." (PMID 30154412, 2018). "There was little evidence of TNF-α production by MAIT cells in response to the mock-treated breast carcinoma lines, whereas the E. coli-treated cells elicited a robust TNF-α response." (PMID 30208917, 2018). "In the present study, we examined the effect of TNF on the expression of the main ganglioside-specific GT genes as well as ganglioside expression in three breast cancer cells from different molecular subtypes." (PMID 29698439, 2018). "High levels of transforming growth factor-β (TGF-β) and pro-inflammatory cytokines such as tumor necrosis factor (TNF) have been reported for breast cancers." (PMID 29921235, 2018). "Our data also revealed that the phosphorylation levels of S6K1 at T389 (p-S6K1T389), which is a well-known mTOR phosphorylation site, increased in breast cancer cells with TNFα treatment." (PMID 30154412, 2018). "Meanwhile, in contrast to Flag-Hsp70 WT and K77R, Flag-Hsp70 K77Q restricted cell growth in the presence of TNFα treatment, suggesting that Hsp70-mediated autophagy is negatively related to cell survival in breast cancer." (PMID 30154412, 2018). "Pro-inflammatory cytokines such as TNF-α have been previously demonstrated to induce EMT in a number of cancers including breast cancer." (PMID 29849939, 2018). "In the case of breast cancer, there is evidence of a synergistic osteoimmunological reaction to T-IMPs as TNF-α is an activator of the R/C promoter for mesenchymal stem cells in the tumor environment of breast cancer via its signal transduction pathway." (PMID 30174768, 2018). "Significant correlations between ERα, TNFα, and NF-κB protein expression have also been reported in breast cancer tissues." (PMID 29463044, 2018). "IKKβ deficiency had little effect on LC3-I and LC3-II expression in TNFα-treated breast cancer cells; however, exogenous ARD1 expression significantly increased LC3-II expression in TNFα-untreated cells." (PMID 30154412, 2018). "Further studies are therefore needed to better understand the precise role played by adipose tumor microenvironment and by adipokines such as IL-6, leptin and TNFα in breast cancer progression." (PMID 29389973, 2018). "Co-culture experiments revealed that adipocytes co-cultured with breast cancer cells overexpress inflammatory cytokines such as IL-6, TNFα, and MMPs, which promote tumor cell invasion." (PMID 29805773, 2018). "Concerning gynecological and breast cancers, in cervical carcinoma, TNF-α (a potent activator of Langerhans cells [LCs]), was constitutively expressed by basal keratinocytes in the normal cervix in an early study." (PMID 30477198, 2018).
breast carcinoma (continued). "Our results show that ACE prevents TNFα-induced migration of MDA-MB-231 metastatic breast cancer cells and inhibits TNFα-induced CXCR3 and CXCL10 expression through inhibition of the IκB kinase (IKK)-mediated NF-κB pathway." (PMID 30177620, 2018). "Our findings are consistent with a recent study that demonstrated a link between heterogeneous enhancement of tumor-adjacent parenchyma on DCE-MRI and dysregulated tumor necrosis factor signaling pathway in breast cancer." (PMID 30176944, 2018). "Using this assay we were able to show that the fusion of human breast cancer cells and human breast epithelial cells was positively triggered by TNF-α in a dose-dependent manner." (PMID 29636110, 2018). "Proinflammatory cytokines and chemokines such as IL-1, IL-6, IL-8, and TNFα, and NF-κB family transcription factors are also recognized as important factors in inflammation and breast cancer." (PMID 29315254, 2018). "NKILA was reported to be upregulated by more than 12-fold by TNF-α- and IL-1β-induced NF-κB activation in breast cancer." (PMID 29379981, 2018). "Another study used three different maturation cocktails (TNF-α/LPS, gold standard, or a mix of Ribomunyl/Imukin) to mature mo-DCs from breast cancer patients and healthy controls." (PMID 30477198, 2018). "Tumor necrosis factor-alpha (TNF-α) is an inflammation cytokine and has been shown to increase the growth of breast cancer cells." (PMID 30155724, 2018). "For example, a yoga intervention in breast cancer survivors reported decreases in IL-6, TNF-α, and IL-1β." (PMID 28694775, 2017). "First, we found that TNFα treatment increased MCF7 cell migration in transwell assay and YAP knockdown reduced TNFα-induced breast cancer cell migration." (PMID 28945218, 2017). "We show that transcription of miR-1246 in MSCs is regulated by CM of ER- breast cancer cells and reveal that miR-1246 enhances NF-κB signaling independently of TNFα." (PMID 28159925, 2017). "Among these cytokines tumor necrosis factor (TNF-α) is always overexpressed in advanced breast cancer." (PMID 28774312, 2017). "Overall, preclinical data using tumor-vasculature-targeted TNF-α has shown improved antitumoral effects of chemotherapeutic agents, obtaining promising results for breast cancer therapy." (PMID 29202842, 2017). "Breast cancer is often accompanied by an inflammatory process characterized by the presence of proinflammatory cytokines such as tumor necrosis factor (TNF-α), which has important implications in the course of the disease." (PMID 29202842, 2017). "In general, the clinical application of TNF-α in breast cancer patients has been restricted because of mild systemic toxicity." (PMID 29202842, 2017). "Our finding provides new insights into the mechanism by which TNF-α up-regulates HBXIP in the development of breast cancer." (PMID 28938560, 2017). "Increased TNF-α levels have been observed in patients with ovarian and breast cancer, and is important in promoting tumorigenesis and metastasis." (PMID 28170411, 2017). "TNF-α strengthened the suppression on the formation of xenografts by chemotherapeutics, confirming that TNF-α preserved synergetic effect on breast cancer growth with chemotherapeutics." (PMID 28127258, 2017). "DAPK3, also called ZIP kinase (ZIPK), has been implicated in interferon γ-and TNFα/Fas-induced cell death and low ZIPK expression was correlated with increased migration and invasion in breast cancer cells." (PMID 28165359, 2017). "In this regard, breast cancer is a complex disease with different stages and molecular signatures, making it difficult to understand the role of TNF-α in this pathology." (PMID 29202842, 2017). "These pathways include Hif-1, AMPK, TNF and calcium signaling, which were reported to be involved in lapatinib-resistance in ErbB2-positive breast cancer cell-lines." (PMID 28288164, 2017). "Previous study found that the expression of NKILA was regulated by TNF-α or IL1β induced NF-κB activation in breast cancer cells." (PMID 28412955, 2017).
breast carcinoma (continued). "In this manner, TNF-α alone or combined with chemotherapy and radiotherapy can function as an adjuvant in the treatment of breast cancer." (PMID 29202842, 2017). "Caspase-8 activity is pre-requisite for Par-4 cleavage in TNF-α induced cell death is reported in breast cancers." (PMID 29278364, 2017). "It suggests that TNF-α is able to enhance the expression of the oncoprotein HBXIP through TNFR1 in breast cancer cells." (PMID 28938560, 2017). "Further studies should be conducted in order to evaluate serum TNF-α and their receptors abundance in distinct breast cancer subtypes before and after conventional treatment." (PMID 29202842, 2017). "A great deal of preclinical research has been undertaken in order to understand the relationship between TNF-α and breast cancer development, progression or as a therapeutic option." (PMID 29202842, 2017). "As expected, stimulation with TNFα increased the expression levels of the investigated cytokines in MDA-MB-231 breast cancer cells significantly compared to unstimulated control (IL-6 4-fold, IL-8 6-fold, MCP-1 5-fold)." (PMID 28832545, 2017). "In conclusion, we presently proved that, TNF-α present radiotherapy- and chemotherapy-sensitizing effect against breast cancer cells." (PMID 28127258, 2017). "Correlation analysis was used to identify the relationship between the SPHK1 expression and cytokines levels, and results indicated a positive correlation between SPHK1 and TNF-α in breast cancer, r = 0.5287, p = 0.0352." (PMID 29186783, 2017). "However, under certain conditions TNF-α can promote signals for activation, differentiation, survival or cell death, so the study of the variants of this cytokine, its receptors, the presence of polymorphisms and its implication in different phenotypes of breast cancer is necessary." (PMID 29202842, 2017). "In this study, we report that TNF-α enhances the growth of breast cancer through up-regulation of oncoprotein hepatitis B X-interacting protein (HBXIP)." (PMID 28938560, 2017). "The induction of interferon β and tumor necrosis factor (TNF) α in cancer cells is responsible for the anti-breast cancer activity of berberine." (PMID 28702078, 2017). "Our data showed that the levels of TNF-α were positively related to those of HBXIP in clinical breast cancer tissues." (PMID 28938560, 2017). "To verify the radiotherapy sensitization effect of TNF-α, we measured the dynamic formation of phosphorylated H2A.X (γ-H2A.X), a marker of DNA double-strand breaks (DSBs), in breast cancer cells after a dose of 40 Gy Cs137-irradiation." (PMID 28127258, 2017). "Changes in TNF-α levels also were observed after aerobic exercise with moderate-intensity in people with PD, and in breast cancer survivors after participating in a yoga program." (PMID 28930237, 2017). "Although over twenty adipokines are known; only twelve (adiponectin, leptin, IL-6, TNF-α, HGF, PAI–1, resistin, secreted frizzled-related protein 5 (SFRP-5), lipocalin 2, IL-8, apelin and visfatin) have been implicated in breast cancer." (PMID 29088874, 2017). "In MCF7, ER positive breast cancer cells, TNFα exposure induced IκBα degradation and phosphorylation of p65 in a time dependent manner." (PMID 28423692, 2017). "Functionally, we provided the evidence that the administration of TNF-α promoted the growth of breast cancer through HBXIP in vitro and in vivo." (PMID 28938560, 2017). "TNF-α was found to increase the efficiency of chemotherapy and radiotherapy against breast cancer cells." (PMID 28881857, 2017). "Most of the breast cancer survivors in this study (>80%) had received a chemotherapeutic cocktail including doxorubicin, which was shown in an animal model to increase TNF-α (and IL-1β) in the hippocampus." (PMID 28616125, 2017). "We provide evidence for the first time that TNF impairs the response to anti-PD-1 not only in mouse melanoma but also in two other experimental cancers (i.e., lung and breast cancer)." (PMID 29273790, 2017).
breast carcinoma (continued). "In this study, we observed that levels of TNF-α were significantly higher in breast cancer patients than controls." (PMID 29088874, 2017). "In function, we demonstrated that the knockdown of HBXIP remarkably abolished the growth of breast cancer mediated by TNF-α in vitro and in vivo." (PMID 28938560, 2017). "Given that MMP9 is regulated by TGF-β and pro-inflammatory TNF/IL-1β cytokines, expression of these cytokines was also examined in human breast carcinomas." (PMID 28423685, 2017). "In summary, we present a model that inflammatory factor TNF-α contributes to the carcinogenesis through activating the oncoprotein HBXIP in breast cancer." (PMID 28938560, 2017). "Conversely, HER2-positive breast cancer cells have been shown to acquire resistance to TNF-induced apoptosis." (PMID 28607534, 2017). "Here we show that yes-associated protein 1 (YAP1), a transcriptional regulator that controls tissue growth and regeneration, has an important role in tumor necrosis factor α (TNF α)-induced breast cancer migration." (PMID 28945218, 2017). "Taking together, our present investigation brought new strategies for breast cancer treatment through sensitized chemotherapy and radiotherapy by TNF-α." (PMID 28127258, 2017). "Cisplatin-treated rats exhibited significantly increased levels of TNF-α (p < 0.001), IL-6 (p < 0.01), and IL-8 (p < 0.001) whereas, significantly decreased the level of IL-10 (p < 0.01) on the 5th day when compared with breast cancer control rats." (PMID 28420987, 2017). "The results showed that wogonoside inhibited growth and metastasis in vivo, and suppressed TNF-α-induced invasion and migration in several breast cancer cells." (PMID 28774312, 2017). "In particular, we have proved that tumor necrosis factor alpha (TNFα) drives MUC4 expression in HER2-positive breast cancer through the activation of NF-kB transcription factor." (PMID 29281999, 2017). "TNF-α strengthened the cytotoxicity of docetaxel, 5-FU and cisplatin against breast cancer cells both in vitro and in vivo." (PMID 28127258, 2017). "The strong impact of CMTM1_v17 in promoting tumor cell proliferation and lead to partial resistance to TNF-α-induced apoptosis likely via activation of NF-κB signaling pathway has been validated in breast cancer." (PMID 28129775, 2017). "Twist1 promoter contains a functional p65-binding motif, several lines of evidence show that TNF-α-mediated Twist1 expression in breast cancer cells contributes to their aggressive phenotype." (PMID 28774312, 2017). "Of note, anti-TNF also synergised with anti-PD-1 in a breast cancer model based on orthotopic graft of 4T1 cells in the mammary fat pad of Balb/c mice." (PMID 29273790, 2017). "Overall our data demonstrate for the first time that the TNF inflammatory pathway upregulates CD47 expression in breast cancer cells." (PMID 28378740, 2017). "NPe derivatives have also been demonstrated to inhibit the TNFα/NFκB signaling pathway in MCF-7 human breast cancer cells." (PMID 29140265, 2017). "In a lung metastasis model of murine breast cancer, TNF-α-activated mesenchymal stromal cells (MSCs) significantly enhanced tumor metastasis via CXCR2+ neutrophil recruitment." (PMID 29202842, 2017). "Mechanistically, CUR pre-treatment ameliorated the cisplatin-induced nephrotoxicity by inhibiting the pro-inflammatory cytokines like TNF-α, IL-6, IL-8, and augmenting anti-inflammatory cytokine (IL-10) in mammary tumor bearing rats." (PMID 28420987, 2017). "As was observed with neutrophils from cancer-free controls, MCP-1, IL1RA, IL1A, and TNF were capable of significantly enhancing the cytotoxic activity of neutrophils from breast cancer patients." (PMID 28721376, 2016). "We found that activation of PKC with subsequent synthesis and release of TNFα can overcome SM insensitivity in breast cancer cell lines of basal phenotype." (PMID 27551497, 2016).
breast carcinoma (continued). "Altogether, obtained results suggest that TNF-α activated MSCs combined with irradiation therapy can serve as new strategy in breast cancer therapy." (PMID 27329316, 2016). "We found that a TNF-α-induced enhancement of breast cancer cell migration was accompanied by an increased secretion of MMP9, but not MMP2, into the culture media." (PMID 27042827, 2016). "Experimental studies showed that the over-expression of P23097 failed to protect DNA fragmentation in leukemia cancer cell line but it converted TNF-sensitive cells into TNF-resistant cells in MCF7 breast cancer cell line." (PMID 27083051, 2016). "In this nested case-control study, we analyzed several biomarkers of inflammation that is ox-LDL, IL-1β, IL-6, TNF-α, WBC, neutrophils, and lymphocytes, and found significant associations between ox-LDL, IL-1β, and TNF-α and post-menopausal breast cancer." (PMID 27391324, 2016). "Wound scratch healing and Transwell migration assays were used to study the effect of TNF-α on the migration of both hormone-dependent and hormone-independent breast cancer-derived cells, i.e., MCF7 and MDA-MB-231, respectively." (PMID 27042827, 2016). "Among patients with breast cancer who were under treatment of coenzyme Q10 (100 mg/day) and vitamin B group (riboflavin 10 mg and niacin 50 mg), inflammatory markers included TNF-α, IL-8, IL-6, IL-1β were significantly decreased." (PMID 27047809, 2016). "Osteoclast activity has also been demonstrated to be stimulated by M-CSF, TNFα and interleukins (IL-8, and IL-11) from breast cancer cells." (PMID 27782035, 2016). "This study evaluated the genetic associations of IL6-174 (rs1800795 G>C) and TNF-308 (rs1800629 G>A) with CACI and cytokine fluctuations within an Asian early-stage breast cancer population." (PMID 27701469, 2016). "For instance, we have recently demonstrated that the fusion of M13SV1 breast epithelial cells and MDA-MB-231 and MDA-MB-435 breast cancer cells is promoted by TNF-α." (PMID 27187369, 2016). "Here, different in vitro assays were employed to assess the effect of TNF-α on breast cancer cell migration." (PMID 27042827, 2016). "In contrast, the means of relative caspase 3 activities showed 1.22- and 1.33-fold in EC-CFUs from 8 breast cancer patients treated with 1 and 10 pg/ml of TNF-α in comparison with those treated with vehicle, respectively." (PMID 27881867, 2016). "We found that TNF-α strongly promoted the migration of both hormone-dependent and highly invasive, triple-negative, breast cancer cells using a Transwell assay and to accelerate wound closure using a scratch assay." (PMID 27042827, 2016). "Breast cancer cells express a number of osteoclast acting factors (PTHrP, IL-11, IL-6, TNFα, M-CSF) to promote RANKL." (PMID 27782035, 2016). "Serum levels of TNF-α have been found to be significantly predictive of breast cancer survival, particularly among women with HER-2 over-expression." (PMID 26970739, 2016). "Stimulation of breast cancer cells with TNFα can lead to decreased E1/E2 ratio, by altering the expression of genes and enzymes involved in E2 activation." (PMID 27160081, 2016). "The activation of TAFs from MSCs in breast cancer, specifically, has been shown to occur via high levels of TNF-alpha and IL-1beta in the tumor microenvironment." (PMID 27515302, 2016). "We describe a patient on adjuvant tamoxifen therapy for breast cancer that was prescribed rifampin for TB prophylaxis prior to initiation of an anti-tumor necrosis factor (TNF)-α agent due to worsening ulcerative colitis." (PMID 27169677, 2016). "Previously our study also found that targeting TNF-a suppressed breast cancer growth and TNF-α monoclonal antibody exerted effectively antitumor activity, which further supported this assertion." (PMID 28115787, 2016). "TNFα has direct tumor-promoting effects and is expressed by ~90% of recurrent breast cancers, including of the Luminal-A subtype." (PMID 27835603, 2016).